TSPO (translocator protein)
Diseases named in the same sentence as TSPO in open-access papers (continued):
Sharing a sentence is not in itself a finding about the gene and the disease.
chronic heart failure (2 papers, 2020 to 2022). "In chronic heart failure, the TSPO PET signal is elevated in the remote myocardium, confirming previous results, but the cellular basis of this signal is difficult to define." (PMID 32125488, 2020). "Whole-body TSPO PET identifies myocardial macrophage infiltration and neuroinflammation after MI, and altered cardiomyocyte mitochondrial density in chronic heart failure." (PMID 32125488, 2020).
chronic lymphocytic leukemia (2 papers, 2015 to 2023). "This protein also contributes to resist the effects of reactive oxygen species in mouse retina, and its expression has been proposed as a prognostic marker in patients with chronic lymphocytic leukemia, in whom lower levels of TSPO correlated with a better response to treatment." (PMID 37092456, 2023). "In the present study, the response of 30 consecutive chronic lymphocytic leukemia (CLL) patients to bendamustine and rituximab treatment was evaluated according to TSPO expression levels." (PMID 25663907, 2015).
germ cell tumors (2 papers, 2016 to 2023). A benign or malignant, gonadal or extragonadal neoplasm that originates from germ cells. "TSPO expression was also correlated with immune cells in other cancers, displaying the strongest association with testicular germ cell tumors." (PMID 38162485, 2023). "Together, these studies suggest that TSPO is regulated during germ cell differentiation and in germ cell tumors." (PMID 27608010, 2016). "Finally, in our search of TSPO role in germ cells, we examined its expression patterns in seminoma, the most common testicular germ cell tumor type in human, proposed to originate from abnormal gonocytes." (PMID 27608010, 2016).
Granuloma (2 papers, 2021 to 2025). A compact, organized collection of mature mononuclear phagocytes, which may be but is not necessarily accompanied by accessory features such as necrosis. "By immunohistochemistry, TSPO staining appeared in association with TB granulomas (and bronchial epithelium; not shown), demonstrating that TSPO expression in pulmonary TB coincides with the occurrence of granulomatous lesions." (PMID 41120776, 2025). "Strong TSPO and CD68 co-staining was observed for macrophages in granulomas." (PMID 34150670, 2021).
hyperglycaemia (2 papers, 2020 to 2021). "In particular, we have demonstrated that, during the early phase of cardiac injury caused by chronic hyperglycaemia, ventricular dysfunction was associated with a change in the outer mitochondrial membrane, characterized by TSPO and VDAC1 overexpression." (PMID 33050121, 2020). "The aim of this work is to better clarify the role of matrix metalloproteinase 2 (MMP-2) isoforms and of translocator protein (TSPO)/voltage-dependent anion-selective channel 1 (VDAC1) modulation in the development of hyperglycaemia-induced myocardial injury." (PMID 33050121, 2020). "Under hyperglycaemia, increased expression of TSPO and VDAC1 was detected." (PMID 33050121, 2020). "Moreover, STZ-induced hyperglycaemia is associated with an increased expression of selective Voltage-Dependent Anion Channel-1 (VDAC1), which contributes, alongside TSPO, to the regulation of calcium traffic at the level of the transition pore of the mitochondrial membrane." (PMID 33477388, 2021). "In this consideration, our study highlights the role of MMP-2 in the regulation of mitochondrial injury mediated by TSPO and VDAC1 in the onset of DCM, thus contributing to the identification of novel potential targets of cardioprotective therapeutic interventions under hyperglycaemia." (PMID 33050121, 2020).
hypogonadism (2 papers, 2020 to 2022). A disorder characterized by decreased function of the gonads. "Therefore, there has been general agreement on the therapeutic value of TSPO as a target for brain pathologies and potentially in conditions of hypogonadism." (PMID 32961709, 2020). "Stimulation of translocator protein within the transduceosome of the testis of SCD mice reverses both hypogonadism and priapism, without affecting intratesticular testosterone production and consequently fertility." (PMID 35592776, 2022). "Because pharmacologic activation of TSPO is independent of LH, it is conceivable that this approach may treat secondary hypogonadism, or mixed primary and secondary hypogonadism, as well." (PMID 35592776, 2022).
Insulin resistance (2 papers, 2023 to 2024). Increased resistance towards insulin, that is, diminished effectiveness of insulin in reducing blood glucose levels. "Previous literature on the possible mechanisms on the associations between insulin resistance and TSPO availability or microglial activation is scarce." (PMID 37113066, 2023). "Based on the previous literature, we hypothesized that metabolic risk factors (insulin resistance, BMI, serum cholesterol values or high sensitivity C-reactive protein) may be associated with TSPO availability and Aβ-accumulation already in cognitively unimpaired individuals." (PMID 37113066, 2023).
ischemia reperfusion injury (2 papers, 2018 to 2024). Adverse functional, metabolic, or structural changes in ischemic tissues resulting from the restoration of blood flow to the tissue (reperfusion), including swelling; hemorrhage; necrosis; and damage from free radicals. "Highlighting the role of TSPO as a chief mediator of post-ischemic arrhythmias, Brown and colleagues observed similar anti-arrhythmic effects of TSPO blockade in a rabbit model of ischemia-reperfusion injury, which were not apparent in those hearts treated with the mPTP blocker, CsA." (PMID 30416455, 2018).
leukemia (2 papers, 2015 to 2023). A malignant (clonal) hematologic disorder, involving hematopoietic stem cells and characterized by the presence of primitive or atypical myeloid or lymphoid cells in the bone marrow and the blood. "Similarly, microglia isolated from TSPO knockout animals had lower ATP synthesis, while TSPO insertion into human leukemia cell lines resulted in increased cellular excitability and ATP production." (PMID 37416505, 2023).
liver diseases (2 papers, 2017 to 2024). "TSPO PET tracer uptake increased in parallel with liver disease severity whether it is in NAFLD or in fibrosis liver models." (PMID 29114179, 2017). "Complementary clinical studies with various liver diseases characterized by inflammatory processes (e.g., viral hepatitis, cholestatic hepatitis, autoimmune hepatitis, and Wilson's disease) are required to evaluate the ability of differential diagnosis of TSPO PET imaging." (PMID 29114179, 2017).
Neonatal sepsis (2 papers, 2018 to 2024). Systemic inflammatory response to infection in newborn babies. "TSPO, ZAP70, CEBPB targeting MAPK14, has-miR-150 targeting BCL11B might affect the pathogenesis of neonatal sepsis." (PMID 30497506, 2018). "These declared that TSPO, MAPK14, and ZAP70 might play critical roles in neonatal sepsis." (PMID 30497506, 2018). "Besides, TSPO, ZAP70, CEBPB targeting MAPK14, has-miR-150 targeting BCL11B might act in the pathogenesis of neonatal sepsis." (PMID 30497506, 2018).
neuropathy (2 papers, 2024). A disorder affecting the nervous system that manifests with pain, tingling, numbness, and/or muscle weakness. "Thus, GRT-X could have an interesting therapeutic potential by combining neuropathy pain relief via the Kv7.2/3 channels with neuroregenerative benefits via TSPO, warranting further translational studies." (PMID 39000434, 2024).
nonalcoholic fatty liver disease (2 papers, 2017 to 2019). "TSPO acts as an imaging biomarker for nonalcoholic fatty liver disease." (PMID 30984779, 2019). "Autoradiography experiments supported in vivo PET data where TSPO tracer binding was not homogeneously distributed in the livers with nonalcoholic fatty liver disease (NAFLD) and in the fibrotic livers (induced by carbon tetrachloride treatment)." (PMID 29114179, 2017).
ovarian carcinoma (2 papers, 2023 to 2024). A malignant neoplasm originating from the surface ovarian epithelium. "Aberrant expression of TSPO has been linked to multiple diseases, including ovarian cancer (OC)." (PMID 36869967, 2023).
porphyria (2 papers, 2015 to 2016). Porphyria is a group of diseases in which substances called porphyrins build up, negatively affecting the skin or nervous system. "Although elevated porphyrins are a hallmark of multiple types of porphyria, the role of porphyrin transporters (TSPO, ABCG2, ABCB6 and FLVCR1) as modulators of disease severity has not been investigated." (PMID 27507172, 2016). "TSPO was found to attenuate plant cell porphyria by delta-aminolevulinic acid levels and the accumulation of tetrapyrroles." (PMID 26175745, 2015).
progressive supranuclear palsy (2 papers, 2020 to 2022). A rare late-onset neurodegenerative disease characterized by supranuclear gaze palsy, postural instability, progressive rigidity, and mild dementia. "TSPO-PET in conjunction with tau- and/or Aβ-PET in cohorts of AD and primary tauopathy patients (i.e., progressive supranuclear palsy or corticobasal degeneration) would translate our present findings into the study of human disease." (PMID 33317543, 2020).
retinal disease (2 papers, 2019 to 2020). "The translocator protein (18 kDa) (TSPO) is described as a biomarker for reactive gliosis, but its biological functions in retinal diseases remain elusive." (PMID 32483169, 2020). "In view of its high expression, TSPO function in RPE cells deserves further studies to elucidate its relevance in retinal disease." (PMID 30777091, 2019).
Senile plaques (2 papers, 2018 to 2023). Senile plaques are extracellular deposits of amyloid in the gray matter of the brain. "As TSPO is an important regulator of neurosteroidogenesis, it is interesting to note that increased microglial and astrocytic TSPO immunoreactivity in the hippocampus of AD patients has been reported, with large clusters of TSPO-positive cells localized in close proximity to senile plaques." (PMID 30344476, 2018). "This suggests that TSPO activation by XBD173 does not affect the phagocytic clearance of the senile plaque but instead confers neuroprotection by interfering with the plaque formation machinery and stopping the formation of senile plaques." (PMID 37891168, 2023).
stress-related disorder (2 papers, 2015 to 2024). Stress-related disorders are mental health disorders that are a result of an atypical response to both short and long-term anxiety due to physical, mental, or emotional stress. "The activation of Translocator protein (18 kDa) (TSPO) has been demonstrated to mediate rapid anxiolytic efficacy in stress response and stress-related disorders." (PMID 25889665, 2015).
ulcerative colitis (2 papers, 2022 to 2026). An inflammatory bowel disease involving the mucosal surface of the large intestine and rectum. "In human patients and animal models of ulcerative colitis (UC), upregulation of the mitochondrial translocator protein (TSPO) in the colon is consistent with inflammation." (PMID 36060674, 2022). "By targeting TSPO, Emapunil exerts anti-UC effects through downregulation of ZBP1, thereby providing a novel mechanism and a potential therapeutic strategy for the clinical management of ulcerative colitis." (PMID 42273694, 2026).
ZIKV infection (2 papers, 2022 to 2023). "TSPO expression in monocytes is worth noting since human monocytes are highly susceptible to ZIKV infection." (PMID 36348095, 2023). "Moreover, due to the complexity of disease, in particular the diversity of TSPO-expressing cells involved in response to ZIKV infection, future studies need to be adequately statistically powered to observe tracer uptake difference between groups." (PMID 36348095, 2023). "Imaging approaches targeted to molecular markers of neuroinflammation, such as the translocator protein (TSPO), may be more appropriate tools for interrogating ZIKV infection and host response in the brain." (PMID 35876869, 2022).
acute respiratory distress syndrome (1 paper, 2023). Progressive and life-threatening pulmonary distress in the absence of an underlying pulmonary condition, usually following major trauma or surgery. "Biomarkers of inflammation such as TSPO are upregulated in activated macrophages in COPD and asthma, as well as malaria-associated acute respiratory distress syndrome (MA-ARDS)." (PMID 38139248, 2023).
adrenocortical carcinomas (1 paper, 2017). "Furthermore, preliminary results on the expression of TSPO in adrenocortical neoplasms in a study performed by our group employing immunohistochemistry demonstrated variable TSPO expression in tumors arising in the adrenal cortex, particularly adrenocortical carcinomas." (PMID 29318061, 2017). "However, we have observed conventional adrenocortical carcinomas with a wide range of TSPO expression, ranging from no expression to markedly increased TSPO expression." (PMID 29318061, 2017).
alcohol hepatitis (1 paper, 2017). "Recent evidences suggest that TSPO might be contribute to the liver damage and alcoholic hepatitis progression." (PMID 29114179, 2017).
anaplastic astrocytoma (1 paper, 2023). "Additionally, IHC was performed on TSPO-knockout microglia and an anaplastic astrocytoma with and without antibody epitope blocking." (PMID 37697350, 2023).
anorexia nervosa (1 paper, 2021). A disorder most often seen in adolescent females characterized by a refusal to maintain a minimally normal body weight, an intense fear of gaining weight, a disturbance in body image, and, in postmenarcheal females, the development of amenorrhea. "It is therefore still unknown if TSPO plays a role in conditions of depleted appetite, such as anorexia nervosa." (PMID 34343461, 2021). "However, neither of these studies have had the statistical power necessary to analyse the effect of anorexia nervosa independently on TSPO expression." (PMID 34343461, 2021). "Undernutrition may also dysregulate TSPO signalling in the brain, given that anorexia nervosa is also considered to be driven by immune processes." (PMID 34343461, 2021). "TSPO PET studies analysing patients with major depressive episodes and serious self-harming behaviour have included patients with anorexia nervosa." (PMID 34343461, 2021). "This analysis also demonstrated the lack of research exploring TSPO's potential involvement in anorexia nervosa." (PMID 34343461, 2021).
Arrhythmogenic right ventricular dysplasia (1 paper, 2025). "The GSEA results show that the TSPO gene may be associated with various cardiovascular diseases in the context of OA, including Arrhythmogenic Right Ventricular Dysplasia (ARVD), Cardiomyopathy with Conduction Disorders (CMC), Dilated Cardiomyopathy (DCM), and Hypertrophic Cardiomyopathy (HCM)." (PMID 39919076, 2025).
arteriosclerosis (1 paper, 2017). A vascular disorder characterized by thickening and hardening of the walls of the arteries. "PET imaging using tracers such as translocator protein, formyl peptide receptor, and COX inhibitors has showed promising results in regards of detecting neuroinflammation, arteriosclerosis and in inflamed lungs." (PMID 27838763, 2017).
astrocytic tumor (1 paper, 2023). A glial tumor of the brain or spinal cord showing astrocytic differentiation.
bone cancer (1 paper, 2022). A primary or metastatic malignant neoplasm affecting the bone or articular cartilage. "Increased IL-6 expression was decreased after MZL injection, indicating that TSPO may play a protective role in bone cancer-induced inflammation." (PMID 36071748, 2022). "TSPO level is increased in both astrocytes and microglia of a rat model for bone cancer pain (BCP)." (PMID 36071748, 2022).
breast adenocarcinoma (1 paper, 2023). "In agreement with previous data reporting higher density of S2R in several lines of breast and pancreatic cancer cells than in the normal (immortalized) cells, pancreatic adenocarcinoma MP and breast adenocarcinoma MCF7 cells were selected because of the density of the TMEM97 and TSPO proteins." (PMID 37047353, 2023).
cerebral cavernous malformation (1 paper, 2023). A disorder characterized by malformations in the structure of the capillaries in the brain. "Our study aimed to explore neuroinflammation using multimodal TSPO PET/MRI imaging for flutriciclamide quantification in cases with cerebral cavernous malformations." (PMID 37089589, 2023).
cerebrovascular disease (1 paper, 2020). "Therefore, in participants with evidence of cerebrovascular disease, TSPO PET studies should adopt blood sampling and full compartment modeling approaches and avoid analyses that depend on reference regions." (PMID 33178101, 2020).
Chronic colitis (1 paper, 2022). A chronic inflammatory disease of the large intestine (colon, cecum and rectum). "To characterize the possible links between intestinal immunity and TSPO, we applied TSPO-KO and TSPO wild type (TSPO-WT) mice to create DSS-induced acute and chronic colitis murine models." (PMID 35269479, 2022).
chronic granulomatous disease (1 paper, 2021). Chronic granulomatous disease (CGD) is a rare primary immunodeficiency, mainly affecting phagocytes, which is characterized by an increased susceptibility to severe and recurrent bacterial and fungal infections, along with the development of granulomas. "The levels of TSPO paralleled the levels of one of the NADPH oxidase subunits (gp91phox) in neutrophils from two types of chronic granulomatous disease patients, one with a deficiency in gp91phox and decreased TSPO and the other with normal levels of both proteins." (PMID 34191248, 2021).
cognitive (1 paper, 2016). "Mice treated with LPS showed cognitive deficits in the novel object recognition test and the Morris water maze test that could be ameliorated by TSPO overexpression." (PMID 27803668, 2016).
colorectal tumor (1 paper, 2025). "TSPO gene expression is elevated in colorectal tumor tissues and is significantly associated with tumor grade." (PMID 40550494, 2025).
Creutzfeldt-Jakob disease (1 paper, 2021). "A single research group published two (R)-[11C]PK11195 reports that showed increased TSPO with varying patterns across subtypes of Creutzfeldt-Jakob disease or Fatal Familial Insomnia." (PMID 34387719, 2021).
diabetic cardiomyopathy (1 paper, 2025). Diabetic cardiomyopathy is a disorder of the heart muscle in people with diabetes. "GA was shown to attenuate diabetic cardiomyopathy by inhibiting ferroptosis and protecting mitochondria via the TSPO/FTMT signaling pathway." (PMID 41415578, 2025). "In conclusion, GA pretreatment attenuated diabetic cardiomyopathy by downregulating TSPO expression, which subsequently promoted FTMT upregulation." (PMID 41415578, 2025).
Dravet syndrome (1 paper, 2021). "Based on our screen, we discovered a Translocator protein (TSPO) ligand, PK11195 as the lead compound and a potential therapeutic target for Dravet syndrome." (PMID 33842883, 2021).
dyslipidaemia (1 paper, 2019). "Thus, altered pancreatic levels of Cyp27A1, ADXR, TSPO and LXRα are triggered in response to genetic obesity in rodents, a condition characterised by dyslipidaemia and hyperinsulinaemia." (PMID 30819824, 2019).